ERCC3 (ERCC excision repair 3, TFIIH core complex helicase subunit)
Diseases named in the same sentence as ERCC3 in open-access papers (continued):
Sharing a sentence is not in itself a finding about the gene and the disease.
ERCC3 also shares sentences with these, for which no sentence is quoted: colorectal cancer (3 papers); Fanconi anemia (3); prostate carcinoma (3); ependymoma (2); lung carcinoma (2); preeclampsia (2); astrocytoma (1); atypical teratoid rhabdoid tumor (1); autosomal recessive disease (1); basal cell carcinoma (1); breast invasive cancer (1); Cerebro-oculo-facio-skeletal-syndrome (1); chronic lymphocytic leukemia (1); developmental delay (1); esophageal cancer (1); esophageal squamous cell carcinoma (1); Ewing sarcoma (1); genetic disorders (1); glioblastoma (1); head and neck cancer (1); hereditary cancer (1); liver cancer (1); lymphoma (1); malignant pleural mesothelioma (1); medulloblastoma (1); neuroblastoma (1); pulmonary hypertension (1); rhabdomyosarcoma (1); sarcoma (1); skin disorder (1).
A further 4 diseases each share a sentence with ERCC3 in 1 paper.